TAS2R13 (taste 2 receptor member 13)
Description:
Receptor that may play a role in the perception of bitterness and is gustducin-linked. May play a role in sensing the chemical composition of the gastrointestinal content. The activity of this receptor may stimulate alpha gustducin, mediate PLC-beta-2 activation and lead to the gating of TRPM5.
Synonyms: T2R13; TRB3
Tractability: Antibody: its Gene Ontology location is reachable by antibodies, with high confidence; UniProt predicts a signal peptide or a membrane-spanning region. PROTAC: a small molecule that binds it is known.
Target class: Membrane receptor; Taste receptor (taste family GPCR); Taste family G protein-coupled receptor
Gene: Protein-coding gene on chromosome 12 (10,907,926 to 10,909,562, reverse strand). Ensembl gene ENSG00000212128.
Subcellular location: Membrane
Pathways (Reactome):
Signal Transduction: Class C/3 (Metabotropic glutamate/pheromone receptors); G alpha (i) signalling events
Sensory Perception: Sensory perception of sweet, bitter, and umami (glutamate) taste
Gene Ontology:
Molecular function: bitter taste receptor activity; taste receptor activity; G protein-coupled receptor activity
Biological process: detection of chemical stimulus involved in sensory perception of bitter taste; positive regulation of cytokinesis; G protein-coupled receptor signaling pathway; sensory perception of taste
Cellular component: membrane; plasma membrane
Genetic constraint (gnomAD): Loss-of-function variants: 1 observed, 1.86 expected, observed/expected ratio (o/e) 0.54, 90% interval 0.18 to 1.77. That is too few expected variants to judge how well the gene tolerates losing a copy. Missense variants: 374 observed, 359.39 expected, observed/expected ratio (o/e) 1.04, 90% interval 0.95 to 1.13. Synonymous variants: 126 observed, 130.22 expected, observed/expected ratio (o/e) 0.97, 90% interval 0.84 to 1.12.
Homologues: Orthologues: chimpanzee TAS2R13 (96% identical), macaque TAS2R13 (87% identical), rabbit TAS2R13 (58% identical), mouse Tas2r121 (57% identical), mouse Tas2r102 (50% identical), rat Tas2r102 (50% identical), mouse Tas2r124 (49% identical), rat Tas2r124 (47% identical). Paralogues in human: TAS2R14 (48% identical), TAS2R46 (45% identical), TAS2R30 (44% identical), TAS2R31 (44% identical), TAS2R43 (44% identical), TAS2R50 (43% identical), TAS2R19 (43% identical), TAS2R20 (42% identical), TAS2R7 (39% identical), TAS2R9 (38% identical), TAS2R10 (35% identical), TAS2R3 (35% identical), and 11 more.
Diseases named in the same sentence as TAS2R13 in open-access papers:
TAS2R13 is named in the same sentence as 1 disease in open-access papers, as found by Europe PMC text mining. Sharing a sentence is not in itself a finding about the gene and the disease.
TAS2R13 shares sentences with these, for which no sentence is quoted: glaucoma (1 paper).